RAB20 (RAB20, member RAS oncogene family)
Diseases named in the same sentence as RAB20 in open-access papers (continued):
Sharing a sentence is not in itself a finding about the gene and the disease.
tumor (5 papers, 2020 to 2025). "High RAB20 expression promotes tumor progression and cell proliferation, inducing G2/M cell cycle arrest via the Chk1/cdc25c/cdc2-cyclinB1 pathway." (PMID 35267417, 2022). "Especially, 15 pairs of corresponding samples were included in the cohort, and the same results were observed that RAB20 mRNA levels were significantly higher in tumor tissues than they were in corresponding normal tissues (t = 3.779, p < 0.001)." (PMID 35267417, 2022). "As detected by IHC, RAB20 had weak and faint expression in the normal cells, while it was strongly and diffusely expressed in tumor cell cytoplasm with sporadic staining in the nucleoplasm." (PMID 35267417, 2022). "Rab20 overexpressing cells suppressed tumour development with smaller tumours formed when compared to Vector cells." (PMID 34401050, 2021). "Consistent effect of EVs obtained from Rab20 knockdown cells in enhancing the formation of microvessels in tumours was seen in matrigel plug in vivo angiogenesis assay." (PMID 34401050, 2021). "As tumours derived from Rab20 overexpressing cells showed reduced angiogenic potential, the ability of EV released by cells with Rab20 deregulation in angiogenesis was explored." (PMID 34401050, 2021). "The results suggested that Ikaros exerts its tumor suppressor activity by regulating RAB20 expression and demonstrate the role of CK2 and PP1 in regulating the Rab20 signaling pathway." (PMID 32138279, 2020). "Its dysregulation can promote the occurrence of HCC, and the tumor suppressor effect of RAB20 may be attributed by the release of extracellular vesicles." (PMID 41153010, 2025). "In this study, it was revealed that RAB20 was significantly lowly expressed in OS samples and metastatic samples, and patients with high expression of RAB20 had a longer survival period, indicating that RAB20 may exert tumor-suppressive properties in OS." (PMID 41153010, 2025). "Moreover, RAB20 was found to be a strong independent prognostic indicator of poor clinical outcomes, identifying PSCC patients with an increased risk for tumor progression and a shorter survival time." (PMID 35267417, 2022). "Overall, we found that RAB20-mediated cancer progression could be tumor-type specific and promotes PSCC proliferation by regulating G2/M cell cycle checkpoints." (PMID 35267417, 2022). "Furthermore, by using newly established PSCC cell lines and animal models, we demonstrated that RAB20 promotes cell proliferation and tumor progression, inducing the G2/M phase cell cycle via the Chk1/cdc25c/cdc2-cyclinB1 pathway." (PMID 35267417, 2022). "Furthermore, tumorigenesis assays demonstrated that RAB20 knockdown inhibited cell proliferation, migration, and colony formation in vitro and tumor growth in vivo." (PMID 35267417, 2022). "This study has uncovered an unrecognized function of Rab20 and its association with EV activities in HCC carcinogenesis, and revealed the functions of HCC cell‐derived EVs in the induction of aerobic glycolysis in tumour cells." (PMID 34401050, 2021). "In this study, we found that the expression of RAB20, a small GTPase family member located on chromosome 13q34, was upregulated in PSCC matched tumor tissues, especially in metastatic lymph nodes." (PMID 35267417, 2022). "Compared with that in normal epithelial cells or tissues, RAB20 protein was overexpressed in five PSCC cell lines and tumor tissues." (PMID 35267417, 2022). "We observed that knockdown of RAB20 in our newly established PSCC cell lines repressed colony formation, cell proliferation, and migration along with repressing tumor growth in xenograft nude mice." (PMID 35267417, 2022). "qPCR, WB, and IHC further confirmed that RAB20 was overexpressed in the cytoplasm of five PSCC cell lines and 78 PSCC tumor tissues compared with that in the corresponding normal controls." (PMID 35267417, 2022).
tumor (continued). "Tumours derived from Rab20 cells showed reduced expressions in the angiogenic marker CD31 and Ki67, suggesting reduced angiogenic and proliferative abilities of the tumour cells." (PMID 34401050, 2021). "Taken together, our study provides a mechanistic link among tumour cell‐derived EVs and glucose metabolism in HCC with Rab20 deregulation." (PMID 34401050, 2021). "We found that rescuing Rab20 in HCC cells abrogated the ability of cell growth, cell motility and tumour formation." (PMID 34401050, 2021). "In the external dataset GSE16088, DDX39A and U2AF1 were significantly highly expressed in tumor samples, and RAB20 was significantly lowly expressed in tumor tissues, and PPP1R3 was significantly highly expressed in tumor samples, which was inconsistent with the results in the GSE39262 dataset." (PMID 41153010, 2025). "Our findings suggest that the overexpression of RAB20 in PSCC may be an initiator of the cellular dysregulation, which acts as an upstream regulator in the G2/M cell cycle phase promoting tumor proliferation and progression." (PMID 35267417, 2022). "The data revealed an intersection of CK2 kinase and PP1 phosphatase signaling via phosphorylation and/or dephosphorylation of the Ikaros tumor suppressor and show that CK2 and PP1 signal transduction pathways have opposing effects on the expression of the Rab20 small GTPase." (PMID 32138279, 2020).
cancer (3 papers, 2018 to 2022). A tumor composed of atypical neoplastic, often pleomorphic cells that invade other tissues. "RAB20 belongs to the Rab family of small GTPases, which plays a critical role in membrane trafficking in epithelial cells and has been found to be associated with the progression of several cancers." (PMID 35267417, 2022). "RAB20 was an unfavorable independent prognostic indicator in the survival analysis (p = 0.011, HR = 2.090; 95% Cl: 1.183–4.692), and PSCC patients with high RAB20 expression experienced shorter 5-year cancer-specific survival times (p < 0.001)." (PMID 35267417, 2022). "Despite the fact that Rab20 has been reported to be overexpressed in various carcinomas, little is known about the functions and mechanistic basis of Rab20 in carcinogenesis." (PMID 34401050, 2021). "RAB20, a member of the RAS GTPase oncogene family, is overexpressed in several cancers with poor outcomes, promoting tumorigenesis and inducing genomic instability." (PMID 35267417, 2022).
infection (2 papers, 2017 to 2025). The state of being infected such as from the introduction of a foreign agent such as serum, vaccine, antigenic substance or organism. "In resting macrophages, endogenous Rab20 was present mostly on early Mtb phagosomes and IFN-γ enhanced the association of Rab20 with Mtb phagosomes, especially at 24 hr after infection." (PMID 28494243, 2017). "For instance, among the genes upregulated in infected wild‐caught birds reported here, RAB20 was also upregulated in 'amakihi surviving experimental infection, and three upregulated genes (COG5, BOD1, and PCDH10 which activates PCDHGA6) were downregulated in 'amakihi that perished." (PMID 40909016, 2025). "EGFP-Mtb burden in vivo was higher in the lungs of Rab20 KO mice only at 7 days after infection." (PMID 28494243, 2017). "However, the EGFP-MtbΔRD1 burden in lungs was higher in Rab20 KO mice relative to control mice for up to 50 days after infection." (PMID 28494243, 2017). "Moreover, RAB20 appears to respond to Plasmodium itself: infection with P. berghei resulted in upregulation of host RAB20 and other Rab genes, and surviving 'amakihi upregulated RAB20 during infection." (PMID 40909016, 2025). "Therefore, increasing expression of RAB20, as observed here in wild infected 'amakihi, could improve the probability of surviving infection with P. relictum." (PMID 40909016, 2025). "Notably, in Rab20 KO BMM, the number of leaky phagosomes that did not retain the probe during 24 hr after infection was significantly higher, with a 2-fold reduction of leaky phagosomes that were able to recover membrane integrity." (PMID 28494243, 2017).
RAB20 also shares sentences with these, for which no sentence is quoted: adenoma (1 paper); atherosclerosis (1); B-cell acute lymphoblastic leukemia (1); bladder cancer (1); Candidemia (1); cerebral infarction (1); hypothyroidism (1); mild cognitive impairment (1); myelodysplastic syndrome (1); obstructive sleep apnea (1).